SRC (SRC proto-oncogene, non-receptor tyrosine kinase)
Diseases named in the same sentence as SRC in open-access papers (continued):
Sharing a sentence is not in itself a finding about the gene and the disease.
tumor (continued). "In the presented case, comprehensive characterization of tumor biology through mRNA sequencing and kinome profiling revealed a number of therapeutic options, specifically Trop-2/PVRL4 or SRC inhibition." (PMID 40427091, 2025). "Consistent with the tumor inhibitory effect of FZD6 knockdown, the activities of proteins that promote tumor growth including SRC, AKT1, and STAT3 were decreased." (PMID 41286306, 2025). "Macrophages in the TME uptake lactate derived from the tumor, which further promotes the ENSA-K63la/SRC-pS12/STAT3-pY705 axis and increases CCL2 expression, enhancing the chemotactic effect on monocytes/macrophages." (PMID 39883522, 2025). "Thus, inhibition of SRC could have a broad impact on tumor progression." (PMID 40481178, 2025). "10%–14% of primary tumor samples exhibited copy number gain and aberrant mRNA expression in both FAK (PTK2) and SRC, consistent with prior studies." (PMID 40959971, 2025). "SRC and YAP1 were also upregulated at the protein level in a significant portion of tumor samples in the cohort." (PMID 40959971, 2025). "Overall, we noted a significant hypomethylation in tumor tissues for most genes in the signature, particularly of OPTN and SRC in KIRC, indicating potential epigenetic regulation." (PMID 39859167, 2025). "Their study revealed that targeting SRC and BRAF had an equivalent or better effect on tumor growth inhibition compared to targeting EGFR and BRAF, similar to our observations." (PMID 40481178, 2025). "Interacting with cellular receptors activates signaling cascades involving SRC and FAK kinases, leading to cytoskeletal reorganization and increased tumor cell motility." (PMID 41304780, 2025). "Four signaling pathways—TGFβ (related to SRC), IL-1 (related to FOS), CXCL, and VEGF (related to CXCL2), were highlighted due to their significant roles in tumor occurrence, progression, and deterioration." (PMID 39770551, 2024). "Consistently, the confusion matrix statistics showed that the normal and tumor samples can be reliably separated using gene expression data for CD2AP, GRB2, WASL, SRC, CTTN, CAPZA1, and Tks4 with 97% sensitivity and 80% specificity." (PMID 39234565, 2024). "While dual inhibition of SRC and ABL is beneficial for the treatment of leukemia, wild-type ABL kinase has been shown to act as a tumor suppressor in many solid tumors." (PMID 39089584, 2024). "On the other hand, PTEN also participates in tumor signaling by dephosphorylating protein targets such as focal adhesion kinase (FAK), insulin receptor substrate 1, c-SRC, and PTEN itself." (PMID 39769140, 2024). "Wound healing experiments and Transwell assays revealed diminished migration and invasion capabilities of EC cells upon SRC silencing and DOX treatment, suggesting inhibited tumor progression." (PMID 39664567, 2024). "Activation of SRC has been shown to activate downstream pathways like, e.g., the PI3K-AKT pathway, playing an essential role in cell proliferation, survival, growth, tumor initiation, metastasis, and drug resistance (for review see:)." (PMID 38674157, 2024). "Activation of LDHA was closely related to phosphorylation of LDHA at Tyr10 by SRC or HER2, promoting cell invasion and tumor cell metastasis, and was correlated with poorer prognosis." (PMID 38301894, 2024). "PRRX1 overexpressed in MPNSTs directly interacts with topoisomerase 2 A (TOP2A) to cooperatively promote epithelial-mesenchymal transition and increase expression of tumour malignancy-related gene sets including mTORC1, KRAS and SRC signalling pathways." (PMID 38448751, 2024). "FAK regulates the expression of the cell cycle protein cyclin D or apoptosis through SRC/ERK, JNK, or PI3K/AKT signaling, thereby affecting cell survival and tumor growth." (PMID 38267463, 2024). "Previous studies have shown that Gas6 is able to regulate tumor cell migration and invasion through the JAK2/ERK, SRC, and Akt/GSK-3β/β-catenin pathways." (PMID 39451556, 2024).
tumor (continued). "Our findings revealed that the expression levels of TOP3A, SRC, and BUB3 were significantly elevated in the tumor groups of both the TCGA and GEO cohorts." (PMID 38825615, 2024). "Western blots confirmed downregulation of SRC/YAP1 and SRC/RHOA signaling axis in the DAB2 downregulation cells, and validated tumor growth inhibition of DAB2." (PMID 38481347, 2024). "We observed that kinase activity profiles varied between tumor intrinsic subtypes, with a highly hyperactive Phos2 (hyperactivity of PI3K/AKT and mTOR signaling members, PTK2, SRC, EPHA2 kinases) and a less active Phos1 subtype." (PMID 38650175, 2024). "Western blot analysis showed that RGD treatment increased the level of MST1/2, LATS1 and YAP phosphorylation but markedly reversed the elevated levels of FAK, SRC and AKT phosphorylation induced by VPS35 overexpression in tumour cells." (PMID 37950040, 2024). "Also, a recent study indicated that CRC tumor with mutations in the G12 residue of KRAS may not benefit from combining SRC and MEK inhibitors." (PMID 36952536, 2023). "Flow cytometry analysis of the BCSC population and tumorsphere growth assay also revealed that downregulation of SRC dramatically reduced the percentage of CD44+/CD24−/low population, and the tumor cell self-renewal ability." (PMID 36633714, 2023). "Mechanistically, we uncovered SPRY2 interfered with SRC-LDHA interaction to inhibit LDHA phosphorylation and suppress glycolysis in tumor stroma." (PMID 37507768, 2023). "All these data demonstrated that SRC expression was upregulated in TNBC tissues and its expression level was positively correlated with the tumor malignancy." (PMID 36633714, 2023). "SRC was overexpressed in TNBC patient tissues and its expression level was highly correlated with the tumor malignancy." (PMID 36633714, 2023). "Accordingly, co-upregulations of SRC and YAP1-KLF5 module in TNBC tissues were significantly positively correlated with the tumor malignance." (PMID 36633714, 2023). "Consistent with the INPP4B tumor suppressor function, the tumorigenic markers MAPK, SRC, and SNAI2 were elevated, and the tumor suppressor proteins RB1, BRCA1, and CHEK2 were decreased in the cells treated with siRNA targeting INPP4B." (PMID 38001678, 2023). "L1 cell adhesion molecule has been demonstrated to facilitate ovarian cancer cell spheroid formation, tumor initiation, and chemoresistance by triggering FGFR1 and its downstream SRC/STAT3 pathway." (PMID 37750089, 2023). "In the cases of invasive BC from the TCGA database in UALCAN, the mRNA levels of AKT1, ESR1, HSP90AA1, CASP3, SRC, and MDM2 were significantly increased in tumor tissues." (PMID 36882618, 2023). "For each tumor, we generated multiple gene expression signature scores measuring MEK pathway activation, MEKi “bypass” resistance, SRC activation, dasatinib sensitivity, EMT, PC1, Hu-Lgr5-ISC, Hu-EphB2-ISC, Hu-Late TA, Hu-Proliferation, and WNT activity." (PMID 35272617, 2022). "Significant correlations were observed between the expression of DDR1, EGFR, and SRC/BCR axis, indicating its active involvement in COAD [source: GEPIA; datasets, TCGA (tumor), GTEx (Normal)]." (PMID 35664781, 2022). "Inhibition of PDK4 suppressed migration and invasion in vitro and tumor growth in vivo through the extracellular signal-regulated kinase (ERK), SRC, and JNK pathways." (PMID 36362028, 2022). "Phosphorylated FAK forms a complex with SRC, which activates downstream signaling pathways such as PI3K/Akt, MAPK, and Rho, promoting the proliferation, survival, and protein synthesis of tumor cells." (PMID 35965583, 2022). "For tumour cell migration, AURKA induces the expression of SLUG, FNB1, and MMP and activates signalling pathways that promote tumour cell migration, including AKT, MAPK, cofilin-F-actin, SRC, and MCAK, to promote tumour cell migration." (PMID 36471438, 2022).
tumor (continued). "Cabozantinib was also predicted to impair proliferative signals in mRCC tumours through effectors involving the MAPK–kinase family, JAK-STAT, PI3K and ERK pathways, and proto–oncogenes such as c-SRC." (PMID 35106125, 2022). "It has been previously shown that SRC protein is strongly expressed in both MPM cell lines and tumor samples." (PMID 35392170, 2022). "Immunofluorescent immunohistochemistry (IHC-IF) staining of pSTAT3 and pSRC on these tumor slices showed that STAT3 activity and SRC activity were dramatically downregulated by Niraparib treatment." (PMID 36324587, 2022). "Specifically, SRC-mediated tyrosine phosphorylation of EGFR regulated its receptor function, as well as its oncogenic role in tumor progression." (PMID 36581908, 2022). "c-SRC is highly expressed and activated in both MPM cell lines and MPM tumor samples, and dasatinib treatment induces cell cycle arrest and inhibits the migration and invasion of MPM cells." (PMID 35392170, 2022). "It is known that SRC activity and expression is increased in CRC tumors as compared to the SRC activity found in normal colon tissue and that SRC activity increases with CRC tumor progression and metastasis." (PMID 35326598, 2022). "FBXL7 gene functions are poorly understood, but the gene’s role as a tumor suppressor has been proposed based on its target proteins, AURKA, BIRC5 and c-SRC." (PMID 35887149, 2022). "After collecting the tumor samples, we analyzed the protein expression of PDK4, p-ERK, p-SRC, and p-JNK by IHC staining." (PMID 36362028, 2022). "Our previous studies in LUAD lines that express readily detectable levels of DLC1 protein indicated AKT and SRC kinases directly phosphorylate and attenuate the Rho-GAP and tumor suppressor activities of DLC1." (PMID 34862367, 2021). "We posit that CCT3833 inhibits tumor growth in RAS-mutant models through on-target inhibition of BRAF and CRAF, and additional on-target inhibition of SRC." (PMID 33130216, 2021). "Phosphorylation by SRC activates SIAH2, which is necessary and sufficient for SRC-mediated degradation of CCAAAT/enhancer binding protein delta (C/EBPδ), a protein with tumor suppressive function." (PMID 33842469, 2021). "Cell 3 also presented the dysregulation of other targetable pathways such as SRC and ERK, widely investigated in several tumor types." (PMID 33917394, 2021). "Using transwell assays, we found that YAP promoted PLC/PRF/5 cell migration, which was attenuated by SRC knockdown, indicating that YAP enhances tumor cell migration, at least partially through SRC." (PMID 34862372, 2021). "We unveiled L1CAM as a master regulator of OCSC pathophysiology through a previously unrecognized L1CAM/FGFR/SRC/STAT3 signaling pathway, thus shedding light on novel molecular mechanisms that sustain the tumor-supporting function of OCSC." (PMID 34645505, 2021). "We show that CCT3833 inhibits RAF and SRC in KRAS-mutant tumors in vitro and in vivo, and that it inhibits tumor growth at well-tolerated doses in mice." (PMID 33130216, 2021). "Overexpressed ASPH directly interacts with ADAM12/15 and strengthens the SRC activation by these proteins which promotes MMP-mediated extracellular matrix degradation and tumor invasiveness." (PMID 32811566, 2020). "The combination of SRC inhibitors and anti‐HER2 therapy is effective against primary tumors, but acquired resistance of SRC inhibitors to tumor cells remains a therapeutic impediment." (PMID 32253815, 2020). "The YAP1/TEAD1 protein complex had the capability to influence downstream cytoskeletal proteins by regulating SRC transcription; therefore, it converts NF to CAF, and CAF can significantly promote tumour growth and metastasis." (PMID 32066485, 2020). "Data on gender, age, tumor location, gastrectomy, tumor size, vessel invasion, perineural invasion, tumor–lymph node–metastasis (TNM) classification, T category, N category, SRC status, and adjuvant therapy strategies were collected for analysis." (PMID 33324548, 2020).
tumor (continued). "Taken together, our results demonstrate that simultaneous blockade of JAK/STAT3, PI3K/AKT/mTOR, SRC and MEK/MAPK pathways results in better anti-tumor activity compared to inhibiting any one or two or three of these signaling pathways." (PMID 32927828, 2020). "Two main pathways, Notch and SRC, through which ASPH promotes the tumor growth have been identified." (PMID 32811566, 2020). "Notch and SRC signaling are probably major pathways influenced by ASPH and contributing to increased aggressiveness of tumor cells that was verified in in vivo models." (PMID 32811566, 2020). "The regulation of the proliferation, invasion and metastasis of tumor cells allows for the interaction of phosphorylated FAK and SRC with the STAT3 signaling pathway." (PMID 33240810, 2020). "SRC activation triggers downstream signaling through the RAS/MAPK and PI3K/AKT pathways, promoting tumor proliferation, survival, and invasion." (PMID 32545574, 2020). "The transformation of SRC from inactivity to active conformation triggers the secretion of VEG through SRC/VEGF signal transduction pathway, which leads to the increase of tumor angiogenesis." (PMID 32547401, 2020). "Further, claudin-7 inhibits ERK and SRC signaling, therefore suppressing EMT and tumor progression in colorectal cancer cell lines." (PMID 31316506, 2019). "Similarly, αVβ3-positive adhesomes promote SRC-CAS (Rous sarcoma oncogene cellular homolog-Crk-associated substrate)-dependent cell survival independently of FAK and cell adhesion, thereby pointing to a role for αVβ3 anchorage-independent tumor cell growth, survival, and aggressiveness." (PMID 31336983, 2019). "Like flavonoid molecules, another ATF6 inhibitor melatonin modulates important kinases FAK, SRC and ROCK1 involved in tumor migration." (PMID 31064137, 2019). "In breast cancer, nobiletin has been found to significantly inhibit the protein tyrosine kinase 2 (PTK2)/SRC/STAT3 angiogenetic signaling pathway, and, consequently, tumor proliferation." (PMID 31354472, 2019). "SRC plays additional important roles in CRC cell survival and in angiogenesis, which are necessary for tumour progression." (PMID 31091767, 2019). "SRC inhibition was also shown to overcome resistance to HER2 inhibitors, restoring lapatinib sensitivity, and to reduce tumor growth in Met-driven tumors." (PMID 31731442, 2019). "SRC is frequently activated in CRC and higher SRC activity is common in metastases compared with the primary tumour." (PMID 31091767, 2019). "Consistently, we found that blocking SRC reduced YAP/TAZ activity and impaired tumor growth and metastasis." (PMID 30559289, 2019). "Several studies indicate that SRC can affect major oncogenic pathways (e.g., the integrins, RTKs, WNT/β-catenin, Yes associated protein (YAP)/tafazzin (TAZ) and JAK/STAT signalling cascades) by direct or indirect mechanisms, and this may partly explain its tumour function." (PMID 31091767, 2019). "As such, it is worth noting that immunohistochemical analysis can determine the levels of phosphorylated SRC and nuclear YAP/TAZ in human tumor biopsies." (PMID 30559289, 2019). "As a tumor suppressor factor, SRCIN1 activates SRC tyrosine kinase (Csk) to inhibit SRC activation in tumor cells." (PMID 29739921, 2018). "The HGF/c-Met axis, which can interact and cooperate with other types of tyrosine kinases, can stimulate various downstream signaling pathways in tumor cells, such as PI3K/AKT, JAK/STAT, Ras/MAPK, SRC, and Wnt/β-catenin, among others." (PMID 29455668, 2018). "In gene expression studies of SRC transformed by several cells, the genes IL8/CEF4, VIP, HMOX1, PLCPI, and UPP1 were identified as signature SRC aggressive tumor genes." (PMID 28945796, 2017). "The possible anti-tumour mechanism is that rGal3C disrupts Galectin-3-integrin clustering on the cell surface, resulting in suppression of integrin/FAK/SRC pathway and subsequent down-regulation of NDRG1 expression." (PMID 28701735, 2017).
tumor (continued). "Our study provides valuable insight into the anti-tumour mechanism of rGal3C in HCC on a proteomics level and is the first to reveal the possible mechanism involving integrin/FAK/SRC pathway and NDRG1." (PMID 28701735, 2017). "In tumor cells treated with PGE2 for 60 min the levels of AREG and EREG increased, whereas in the presence of c-SRC inhibitors (PP1 or SU6656) or ADAM-MMPs inhibitor (GM6001), AREG and EREG levels declined towards the baseline." (PMID 28415726, 2017). "SRC is a proto-oncogene that acts upstream of RAS, and activates the oncogenic RAS pathway by phosphorylating SHC in tumor cells." (PMID 28815022, 2017). "FAK signaling has been shown to regulate proteins (e.g. SRC, SYK, FYN, LYN, GRB2, PI3K, and paxillin) that are involved in modulating cytoskeleton rearrangements to enhance tumor growth and metastasis." (PMID 27472394, 2016). "MDA-9/Syntenin (SDCBP) is a scaffold protein that interacts with a remarkable repertoire of key regulatory proteins, including SRC, FAK and EGFR, which are often related to expression of the tumor phenotype and cancer progression." (PMID 27472461, 2016). "The present study shows that SRC and MEK co-inhibition by Saracatinib and PD0325901 respectively can be broadly effective in tumor growth control of a wide panel of NSCLC cell lines." (PMID 26358373, 2015). "The co-inhibition of MAPK and SRC induced strong G1/G0 cell cycle arrest in the NSCLC lines, inhibited anchorage independent growth and delayed tumor growth in H460 and H358 mouse xenografts." (PMID 26358373, 2015). "This is consistent with findings by two other groups whereby inhibiting both SRC and MEK signaling suppressed the invasive growth and cellular survival of tumor cells." (PMID 26358373, 2015). "In this study, we demonstrate that co-inhibition of the MAPK and SRC pathways using a PD0325901 and Saracatinib kinase inhibitor combination can abrogate tumor growth in NSCLC." (PMID 26358373, 2015). "show that the clinical phenotype is driven by both RASSF1A loss and the independently transcribed RASSF1C isoform, which promotes SRC activation, pseudo-EMT, and β-catenin/YAP1-dependent invasion of tumor cells." (PMID 26549256, 2015). "SRC, LYN and CKB immunoreactivity was detected in 72 (52.2%), 66 (47.8%) and 0 (0%) of the tumor samples." (PMID 26460485, 2015). "A gradual decrease in the percentage of SRC and LYN methylation was observed corresponding to the tumor stage (p < 0.008, for most of the comparisons; Mann-Whitney test followed by Bonferroni correction)." (PMID 26460485, 2015). "Like SRC, TGF-β/ALK5 signalling is currently targeted in the experimental and clinical treatment of various tumours." (PMID 26588899, 2015). "c-MYC, SRC and YAP1 were expressed in most samples (WT and control rhabdoid tumours) with c-MYC elevated in NCAM+ALDH1+ tumour." (PMID 23239665, 2013). "HSP90 is also involved in tumor cell migration through client proteins including c-MET, SRC and FAK." (PMID 22439642, 2012). "In vivo, the combined therapy markedly reduced the expressions of SRC and JUNB in tumor tissues." (PMID 40599804, 2025). "The immunohistochemistry images revealed that SRC was located mainly in the cytoplasm of the tumor cells; JUNB and FOSB were located mainly in the cell nucleus; and PD-L1 was located mainly in the cytoplasm and nucleus of the tumor cells." (PMID 40599804, 2025). "The top five genes with the highest degree values are AKT1, SRC, EGFR, BCL2, and CASP3, suggesting that FOA may exert its anti-tumor effects by acting on multiple targets." (PMID 41050420, 2025). "Interestingly, RNA expression in tumor tissue was only evident for CEACAM1, MAGEA4, SRC, TPBG, GPA33, and SUB1, with the highest and lowest expression for SRC and MAGEA4, respectively." (PMID 39949781, 2025). "Although SRC itself is not typically an initiating factor in tumorigenesis, it plays a pivotal role in supporting tumor growth and survival." (PMID 40650282, 2025).